ANXA2 (annexin A2)
Diseases named in the same sentence as ANXA2 in open-access papers (continued):
Sharing a sentence is not in itself a finding about the gene and the disease.
glioma (continued). "Differently, ANXA5 is regarded as a potential early biomarker in hepatocarcinogenesis together with ANXA2 and a predictive biomarker for tumor progression in different cancer types, but it was not so far identified as a specific oncogenic protein in gliomas as well as CAPZB and CAPZA1." (PMID 38607010, 2024). "However, whether ANXA2 is involved in the oncogenic functions of miR155HG in glioma has not been determined." (PMID 30898167, 2019). "Furthermore, Kaplan–Meier curve and Cox regression analyses showed that the high expression of ANXA2 and its pseudogenes were correlated with the poor OS of glioma patients, and the aberrantly expressed ANXA2, ANXA2P1 and ANXA2P2 were the independent prognosis factors for gliomas." (PMID 29291003, 2017). "In addition, while annexin A2 is involved in cell proliferation, migration and invasion, not much is known about how CTX binding to annexin A2 may hamper glioma invasion in the brain." (PMID 25826056, 2015).
pancreatic cancer (59 papers, 2009 to 2025). "The GEPIA database confirmed a strong association between MMP28 and ANXA2 expression in pancreatic cancer." (PMID 39972459, 2025). "And downregulation of a phosphorylated ANXA2 correlated with loss of ability in pancreatic cancer cells to undergo TGFβ-Rho mediated EMT." (PMID 29568351, 2018). "Annexin A2 overexpression was also significantly associated with rapid recurrence after gemcitabine-adjuvant chemotherapy in patients with resected pancreatic cancer." (PMID 28886730, 2017). "Collectively, these results clearly suggest that gemcitabine resistance was induced by overexpression of ANXA2 and was linked to the interaction between ANXA2 and p50, which subsequently upregulated anti-apoptotic NF-κB target genes in pancreatic cancer cells." (PMID 25611381, 2015). "This upregulated the genes encoding IL-6, which induced gemcitabine resistance in pancreatic cancer, suggesting that ANXA2 might be a useful therapeutic target." (PMID 39057791, 2024). "Interestingly, annexin-A2 also has been implicated in gemcitabine resistance in pancreatic cancer via the AKT/mTOR pathway." (PMID 29443941, 2018). "Furthermore, in cancer tissue, the surface expression of ANXA2 is associated with pancreatic cancer development." (PMID 24591759, 2014). "In pancreatic cancer, the co-expression of the long isoform of TNC with membrane-associated annexin A2 (ANXA2) and the co-expression of TNC with MMP9 are significant indicators of poor patient prognosis." (PMID 40046232, 2025). "A recent study also shows that Anxa2 can directly regulate NF-κB activation by binding to the p50 subunit in pancreatic cancer cells." (PMID 38253182, 2024). "To test this assumption, we used two different animal models in which inhibition of ANXA2 gene expression and protein function drastically reduced the invasion and metastasis of breast and pancreatic cancer cells." (PMID 38092984, 2023). "ANXA2 immunostaining also suggested that ANXA2 is highly expressed in PANC‐1 pancreatic tumor tissue." (PMID 36453020, 2023). "The choice of ANXA2 as a biomarker was based on previous reports that high ANXA2 levels are strongly correlated to the survival of pancreatic cancer patients, which was also verified by our bioinformatical study." (PMID 36453020, 2023). "Intracellular ANXA2 binds the p50 subunit of nuclear factor (NF)-κB by exposure of pancreatic cancer cells to genotoxic agents." (PMID 36247003, 2022). "This interaction was supported by reduced tPA cell binding and invasion upon the inhibition of ANXA2, confirming the role of surface ANXA2-bound active tPA in promoting local plasmin generation and invasion of pancreatic cancer cells." (PMID 35204653, 2022). "Efficacy of a combination therapy using Listeria has been recently shown in transplantable HCC model and in LmAI-based Annexin A2-targeting cancer immunotherapy in pancreatic cancer models." (PMID 35173308, 2022). "Apart from S100A10, ANXA2 has also been shown to co-localise with S100A6 on the plasma membrane of pancreatic cancer cells and tissue, and together, promoted increased tumour cell motility." (PMID 35204653, 2022). "Collectively, our results suggest that SNHG14 potentiates pancreatic cancer progression through modulation of annexin A2 expression via acting as a competing endogenous RNA for miR‐613." (PMID 31513352, 2019). "Further correlation analysis showed that SNHG14 expression levels were inversely correlated with miR‐613 expression levels and positively correlated with those of ANXA2 in pancreatic cancer tissues." (PMID 31513352, 2019). "Anxa2 overexpression promotes chemoresistance in non-small cell lung cancer, pancreatic cancer, neuroblastoma, and hepatocarcinoma." (PMID 31113450, 2019). "Taken together, this study supports further developing Lm-ANXA2 as a therapeutic agent in combination with anti-PD-1 antibody for pancreatic cancer as well as other cancer types." (PMID 31113479, 2019).
pancreatic cancer (continued). "Annexin A2 (ANXA2) is a pro-metastasis protein, previously identified as a relevant PDAC antigen that is expressed by a GM-CSF-secreting allogenic whole pancreatic tumor cell vaccine (GVAX) to induce an anti-ANXA2 antibody response in patients with PDAC." (PMID 31113479, 2019). "We also found that SNGH14 modulated annexin A2 (ANXA2) expression via targeting miR‐613 in pancreatic cancer cells." (PMID 31513352, 2019). "In pancreatic cancer patient's high stromal ANXA2 level was predictive for reduced disease-free survival and overall survival." (PMID 30627566, 2018). "AnxA2 has been reported to have 5–15 fold higher levels of expression in pancreatic tumors compared to normal pancreatic cells." (PMID 29290958, 2017). "We demonstrate that BDMC represses Annexin A2 in pancreatic cancer cells, which is also dependent on GRP78 activation." (PMID 27845899, 2016). "In pancreatic cancer, ANXA2 is highly expressed, acts as a tPA receptor to activate plasminogen, and consequently increases the invasiveness of pancreatic cancer cells by altering the extracellular matrix." (PMID 24591759, 2014). "It has been shown that ANXA2 can mediate epithelial to mesenchymal transition, invasion, and metastases in pancreatic cancer, for example through translocation from the cytosol to the cell membrane." (PMID 24708694, 2014). "In fact, high levels of annexin A2 correlate with pancreatic cancer recurrence in post-operative patients who were previously treated with gemcitabine adjuvant therapy." (PMID 23519104, 2013). "A more recent study demonstrated that Tyr23 phosphorylation-dependent cell-surface localization of Anxa2 is required for the invasion and metastases of pancreatic cancer." (PMID 23691485, 2012). "And constitutively phosphorylated with Tyr23 leads to the cell-surface localization of Anxa2, which is essential for the invasion and metastases of pancreatic cancer." (PMID 23691485, 2012). "Genes associated with increased cell invasion/motility in breast and pancreatic cancers [ANXA2] were also dysregulated." (PMID 22022533, 2011). "Specifically, 39(75%) of 52 fresh pancreatic tumor tissue samples tested have increasedcell surface expression of ANXA2." (PMID 21572519, 2011). "ANXA2 is a lipid- Ca2+-actin binding protein that has been reported to be upregulated in different human tumors like hepatocellular and pancreatic carcinoma and acute promyelocytic leukemia." (PMID 21436996, 2011). "Furthermore, ANXA2 expression was also increased in MMP28-overexpressing pancreatic cancer cells, and ANXA2 knockdown partially inhibited the ability of MMP28 to promote JNK phosphorylation." (PMID 39972459, 2025). "In gemcitabine-resistant pancreatic cancer, ANXA2 could interact directly with P50 and cotranslocate into the nucleus, thereby modulating NF-κB signaling." (PMID 39057791, 2024). "ANXA2 also seems to participate in the development and progression of pancreatic cancer (PC)." (PMID 39594718, 2024). "Furthermore, our data also supported the YW7 internalization that followed binding to ANXA2 in pancreatic cancer cells, suggesting that YW7 has the potential to guide drugs to recognize tumor cells or even cross the cell membrane." (PMID 36453020, 2023). "Nevertheless, to ensure that results were not specific to the MDA-MB-231 cell line and may concern other invasive cancer cells, AsPC-1 pancreatic cancer cells were studied, showing also a high expression of ANXA2." (PMID 38092984, 2023). "This could be achieved either with anti-ANXA2 antibodies, which have been shown to inhibit metastasis of breast and pancreatic cancer cells, or with small molecule drugs." (PMID 38092984, 2023). "The first study implicating ANXA2 expression with tPA production was conducted in 1998 and demonstrated high expression levels of uPAR and ANXA2 in pancreatic cancer cells compared to normal cultures where both receptors were found to be localised in the basolateral membrane in SK-PC1 cells." (PMID 35204653, 2022).
pancreatic cancer (continued). "Additionally, it was observed that translocation of NFκB1 into the nucleus is facilitated by Annexin A2 and subsequently leads to gemcitabine resistance in pancreatic cancer." (PMID 35896012, 2022). "In addition, ANXA2 is strongly expressed in pancreatic cancer and facilitates pancreatic cancer progression, and literature has also reported the implication of ANXA2 in the prognosis and diagnosis of CRC." (PMID 33407563, 2021). "Thus, KPC mice with identified 3-5 mm pancreatic tumors, were treated with Empty Lm vaccination or Lm-ANXA2 followed by anti-PD-1 antibody, respectively, and were examined by a small animal ultrasound (Vevo770) weekly." (PMID 31113479, 2019). "In addition, pcDNA3.1‐ANXA2 transfection markedly elevated the expression levels of ANXA2 mRNA and protein, and the expression of ANXA2 was significantly up‐regulated in pancreatic cancer cells." (PMID 31513352, 2019). "In addition, the miR‐613 expression level was lower and the ANXA2 mRNA expression level was higher in the pancreatic cancer tissues with high expression of SNHG14 than those with low expression of SNHG14." (PMID 31513352, 2019). "Furthermore, intracellular ANXA2 binds the p50 subunit of nuclear factor (NF)-κB to become the ANXA2-p50 complex when pancreatic cancer cells (MIA-PaCa-2) are exposed to genotoxic agents (such as gemcitabine)." (PMID 29598816, 2018). "Next we examined whether the inactivation of Annexin A2 by gene knockdown reduced NF-кB activity in HepG2 cells, as previously observed in pancreatic cancer cells." (PMID 28963461, 2017). "Importantly, Annexin A2 is over-expressed in various types of tumors, including breast, liver, prostate, and pancreatic tumors." (PMID 28963461, 2017). "In summary, intracellular ANXA2 can directly regulate the transcriptional activity of NF-κB by binding to the p50 subunit of NF-κB, inducing gemcitabine resistance in pancreatic cancer cells through upregulation of anti-apoptotic genes, including that encoding IL-6." (PMID 25611381, 2015). "Mia-Paca2 cells exhibited the lowest levels of ANXA2 expression among several pancreatic cancer cell lines tested; therefore, we constructed stable Mia-Paca2 human pancreatic carcinoma cell lines expressing wild-type or Y23A ANXA2 using a retroviral gene expression system." (PMID 25611381, 2015). "Collectively, our data strongly suggest that ANXA2 is a good biomarker to predict patient outcomes after therapy with gemcitabine and may be a useful therapeutic target for pancreatic cancer." (PMID 25611381, 2015). "Herein the role of intracellular ANXA2 was investigated in a pancreatic cancer cell line." (PMID 25611381, 2015). "We hypothesized that the interaction between ANXA2 and p50 might be related to the accumulation of ANXA2 in the nuclei of pancreatic cancer cells." (PMID 25611381, 2015). "Annexin A2 (ANXA2) was identified as a biomarker for pancreatic cancer." (PMID 24708694, 2014). "Moreover, a positive relationship between the cellular levels of S100A6 and the membrane localization of ANXA2 provides a possible mechanism for ANXA2-related increases in pancreatic cancer cell motility." (PMID 24591759, 2014). "However, higher expression of ANXA2 (2- to 8-fold) is observed in three primary pancreatic tumors and one metastatic tumor compared with normal pancreas." (PMID 24591759, 2014). "Our current findings suggest that SNHG14 potentiates pancreatic cancer progression through modulation of annexin A2 expression via acting as a competing endogenous RNA for miR‐613, and that the SNHG14‐miR‐613‐ANXA2 axis may represent a key signalling pathway for pancreatic cancer progression." (PMID 31513352, 2019). "We have screened an ANXA2‐targeting heptapeptide, termed YW7, based on the phage display technique and found that FITC‐YW7 selectively binds to pancreatic cancer cell PANC‐1." (PMID 36453020, 2023).
pancreatic cancer (continued). "Some of them (ITGA3, CDK1, IFIT3, ANXA1, ANXA2, OAS1, and LACTB) have been studied to varying degrees concerning their relationship with pancreatic cancer." (PMID 36834681, 2023). "LINC00941 interacts with ANXA2 and inhibits NEDD4L-mediated ANXA2 degradation to promote cell proliferation in pancreatic cancer." (PMID 38027016, 2023). "We show here that annexin-A2 (ANXA2) is required for membrane repair in invasive breast and pancreatic cancer cells." (PMID 38092984, 2023). "Mechanistic studies revealed that miR‐613 was targeted by SNHG14, and Annexin A2 (ANXA2) was targeted and inversely regulated by miR‐613 in pancreatic cancer cells." (PMID 31513352, 2019). "MiR‐613 was down‐regulated and ANXA2 was up‐regulated in the pancreatic cancer tissues, and SNHG14 expression levels were inversely correlated with miR‐613 expression levels and positively correlated with the ANXA2 mRNA expression levels." (PMID 31513352, 2019). "Furthermore, ANXA2 amplifies MMP28-mediated M2 TAM infiltration, collectively contributing to the malignant progression of pancreatic cancer." (PMID 39972459, 2025). "We discovered that in pancreatic cancer, LINC00941 acts as a protein decoy in the cytoplasm and confirmed that it can competitively bind to the E3 ubiquitin ligase NEDD4L to inhibit the ubiquitination of ANXA2 and promote its stabilization." (PMID 35977942, 2022). "The study also showed upregulation of ANXA2 in vitro in a gemcitabine-resistant pancreatic cancer cell line (GEM-MIA PaCa-2), where the inhibition of ANXA2 increased the cytotoxic effect of gemcitabine, suggesting its potential role in inducing gemcitabine resistance." (PMID 35204653, 2022). "Interestingly, we found co-expression of ANXA2 with YAP/TAZ in the centroacinar and ductal cells of normal pancreas, as well as in the activated stellate cells of chronic pancreatitis and pancreatic cancer." (PMID 26567630, 2015). "Although cell surface localization of ANXA2 has been reported to have a critical role in the progression and metastasis of a variety of tumors, including pancreatic cancer, the biological role of intracellular ANXA2 is not fully understood." (PMID 25611381, 2015). "Preliminary immunohistochemical staining showed increased expression of ANXA2 and p50 (although their distributions were sparse) and their nuclear co-localization in primary pancreatic cancers (data not shown)." (PMID 25611381, 2015). "Both annexin A2 and TNC were found to be over-expressed and co-localized in high-grade PanIN lesions and PDAC suggesting a potential role of their interaction in advanced stages of pancreatic cancer." (PMID 23519104, 2013). "Other studies have indeed reported the presence of autoantibodies against ANXA2 in systemic autoimmune diseases and lung cancer, as well as pancreatic cancer, suggesting that the humoral response to ANXA2 is not specific for PDAC transformation." (PMID 24010981, 2013). "These were chosen as neither have been previously reported in pancreatic cancer whereas Annexin A2 is a known protein expressed in pancreatic cancer." (PMID 21811618, 2011). "Moreover, inhibiting ANXA2 expression partially reversed the effects of MMP28 on TAMs, suggesting that the MMP28-ANXA2 interaction influences TAM infiltration and polarization, thereby representing a potential therapeutic target for TAM-based pancreatic cancer treatments." (PMID 39972459, 2025).